APOBEC3A (apolipoprotein B mRNA editing enzyme catalytic subunit 3A)
Diseases named in the same sentence as APOBEC3A in open-access papers (continued):
Sharing a sentence is not in itself a finding about the gene and the disease.
autoimmune disease (2 papers, 2023). A disorder resulting from loss of function or tissue destruction of an organ or multiple organs, arising from humoral or cellular immune responses of the individual to their own tissue constituents. "Here, we consider the genes CXCL11, CCL2 and APOBEC3A, as they are connected with autoimmune diseases, including systemic lupus erythematosus and thus potential therapeutic targets in the management of patients with lupus and, likely, other interferonopathies." (PMID 37770709, 2023).
gastric cancer (2 papers, 2018 to 2024). A primary or metastatic malignant neoplasm involving the stomach. "In gastric cancers, mRNA expression levels of AICDA, NFκB p65, CBFβ, APOBEC3A, and APOBEC3B were markedly increased, similar to their expression profiles in gastric mucosae with H, pylori infection." (PMID 30514953, 2018). "As expected, expression levels of AICDA, NFκB p65, CBFβ, APOBEC3A, and APOBEC3B were increased in gastric cancers with higher TNM stage." (PMID 30514953, 2018). "Results showed that expression levels of NKX6.3, CDH1, CDKN1A, and EP300 were decreased while expression levels of NFκB p65, AICDA, CBFβ, APOBEC3A, APOBEC3B, RhoA, ROCK1, ROCK2, PIK3CA, and CCND1 were increased in CagA positive gastric cancers compared to those in CagA negative cases." (PMID 30514953, 2018).
leukemia (2 papers, 2017 to 2023). A malignant (clonal) hematologic disorder, involving hematopoietic stem cells and characterized by the presence of primitive or atypical myeloid or lymphoid cells in the bone marrow and the blood. "High APOBEC3A-expressing leukemia cells require the ATR-Chk1 checkpoint for survival, while blocking this pathway causes cell death." (PMID 38021159, 2023).
liver cancer (2 papers, 2022 to 2024). An epithelial or non-epithelial malignant neoplasm that arises from the liver. "Similarly, higher, likely transient, levels of APOBEC3A through an integrative transposable element can elevate liver cancer rates in Fah liver regeneration models, which are contingent on APOBEC3A catalytic activity." (PMID 38254863, 2024).
lung carcinoma (2 papers, 2022 to 2023). "Our previous report showed an association between age and the impact of the APOBEC3A/B deletion in lung cancer and a similar trend in prostate cancers." (PMID 36394079, 2023). "Given our previous findings of an age‐related trend in the lung cancer risk among individuals with APOBEC3A/B deletion genotype, we performed subgroup analysis by age groups in the endometrial cancer cases and controls." (PMID 36394079, 2023). "In addition, CRISPR-mediated deletion of APOBEC3A significantly reduced double-strand DNA breaks and delayed the emergence of drug resistance, indicating APOBEC3A as a potential target for preventing or delaying acquired resistance in lung cancer therapy." (PMID 36210388, 2022).
lymphoma (2 papers, 2019 to 2022). A malignant (clonal) proliferation of B- lymphocytes or T- lymphocytes which involves the lymph nodes, bone marrow and/or extranodal sites. "Analysis of the Brune lymphoma dataset in the Oncomine database revealed that the APOBEC3A mRNA level in DLBCL was similar to whereas the APOBEC3B mRNA level was higher than that in normal tissue." (PMID 35592333, 2022). "In GCB lymphomas, a significant excess of somatic mutations was detected in both AID and APOBEC3A mutable motifs." (PMID 30759888, 2019). "We also found that APOBEC3B was more highly expressed than APOBEC3A in DLBCL tissues in both the Brune and Compagno lymphoma datasets." (PMID 35592333, 2022). "Similar trends in APOBEC3B and APOBEC3A expression in DLBCL were observed in The Cancer Genome Atlas (TCGA)-based GEPIA database (data not shown), but not in the Compagno lymphoma DLBCL dataset of TCGA." (PMID 35592333, 2022).
pancreatic adenocarcinoma (2 papers, 2018 to 2022). "In pancreatic adenocarcinoma (PAAD) cell lines, both APOBEC3A and UNG expression was significantly negatively correlated (ρ ≤ − 0.819, padj ≤ 0.0001; n = 28 for APOBEC3A and 5 for UNG; Ntests = 26,610) with log(IC50) of the BET inhibitor JQ1." (PMID 29642934, 2018). "However, the role of APOBEC1, APOBEC3A, APOBEC3G and APOBEC3H in pancreatic adenocarcinoma is not clear, and related studies are very scarce, which motivated us to carry out relevant bioinformatics analysis." (PMID 36339709, 2022).
papilloma (2 papers, 2013 to 2014). A benign epithelial neoplasm that projects above the surrounding epithelial surface and consists of villous or arborescent outgrowths of fibrovascular stroma. "However, APOBEC3A also incuded mutation of human papilloma DNA and transfected plasmid DNA." (PMID 24748981, 2014). "The implication of APOBEC3A fits with data from others revealing that enforced expression of APOBEC3A (as well as APOBEC3C and 3H) can lead to mutation of human papilloma viral DNA as well as of transfected plasmid DNA." (PMID 23599896, 2013).
squamous cell carcinoma (2 papers, 2024 to 2025). A carcinoma arising from squamous epithelial cells. "In contrast, in squamous cell carcinoma we find that, there is expansion of GRHL3expression and activity to a subset of cells undergoing DNA replication and concomitant extension of APOBEC3A expression to proliferating cells." (PMID 39548236, 2025). "The identification of GRHL3 as a transcription factor responsible for driving APOBEC3A expression in differentiating keratinocytes and in squamous cell carcinoma highlights the power of single-cell transcriptomics to uncover gene regulatory networks." (PMID 39548236, 2025). "SCENIC analysis of the four SCC datasets implicated GRHL3 as a potential regulator of APOBEC3A in squamous cell carcinoma as well as in healthy epithelia, with strong correlations between GRHL3 activity and APOBEC3A expression evident across all studies (Dataset EV2)." (PMID 39548236, 2025). "In contrast, we show that in squamous cell carcinoma tissues, there is expansion of GRHL3 expression and activity to a subset of cells undergoing DNA replication and concomitant extension of APOBEC3A expression to proliferating cells." (PMID 38496447, 2024).
acute myeloid leukaemia (1 paper, 2025). "As previously reported, APOBEC3A was also highly expressed in acute myeloid leukaemia (LAML), but GRHL3 was not, which is consistent with our earlier conclusion that APOBEC3A is differentially regulated in keratinocytes and myeloid cells." (PMID 39548236, 2025).
autoimmune uveitis (1 paper, 2020). An autoimmune form of uveitis (disease). "Interferon, a regulating cytokine in autoimmune uveitis, can induce APOBEC3A in monocytes." (PMID 32458144, 2020).
B cell lymphoma (1 paper, 2018). "UNG expression was negatively correlated with APOBEC3B expression in mature B cell lymphoma cell lines (MATBCL; ρ = − 0.372, padj = 0.034, n = 60, Ntests = 230) and with APOBEC3A expression in chronic lymphocytic leukemia cells (CLLE; ρ = − 0.324, padj = 0.037, n = 78, Ntests = 230)." (PMID 29642934, 2018).
cervical tumor (1 paper, 2018). "Interestingly, the expression of an APOBEC3B miRNA that could regulate APOBEC3A/3B fusion transcript (miR-34b-3p) was downregulated in cervical tumor samples, suggesting that this miRNA may lead to a loss of miRNA repression and a consequently increased expression level of the APOBEC3A/3B protein." (PMID 29963045, 2018).
cholangiocarcinoma (1 paper, 2023). A carcinoma that arises from the intrahepatic biliary tree (intrahepatic cholangiocarcinoma) or from the junction, or adjacent to the junction, of the right and left hepatic ducts (hilar cholangiocarcinoma). "In cholangiocarcinoma, only APOBEC3A expression was associated with APOBEC3-induced mutation burden." (PMID 36978147, 2023). "Another variant, rs12157810, has also been associated with lower cholangiocarcinoma and gallbladder cancer risk, although it was found to increase APOBEC3A promoter activity." (PMID 36978147, 2023).
colorectal cancer (1 paper, 2024). A primary or metastatic malignant neoplasm that affects the colon or rectum. "In models predisposed to colorectal cancer (ApcMin), the constitutive, ubiquitous expression of human tumor-like levels of APOBEC3A from the CAG promoter can promote the development of colorectal cancer." (PMID 38254863, 2024).
endometrial cancer (1 paper, 2023). Primary or metastatic malignant neoplasm involving the endometrium (mucous membrane that lines the endometrial cavity). "The APOBEC3A/B deletion variant was significantly associated with reduced risk for endometrial cancer among Norwegian women." (PMID 36394079, 2023). "In the present study, we aimed to evaluate the APOBEC3A/B deletion as a potential risk modulating factor for endometrial cancer." (PMID 36394079, 2023). "To estimate the potential impact of the APOBEC3A/B deletion variant on endometrial cancer risk, we compared the frequency of the APOBEC3A/B genotypes among endometrial cancer patients (1470) to those of the healthy controls (1918)." (PMID 36394079, 2023). "The APOBEC3A/B deletion polymorphism is associated with a decreased risk of endometrial cancer in the Norwegian population." (PMID 36394079, 2023). "We found the APOBEC3A/B deletion variant to be significantly associated with reduced risk of endometrial cancer among Norwegian women (OR = 0.75; 95% CI = 0.62–0.91; p = 0.003; dominant model)." (PMID 36394079, 2023). "Whether this may be the case for endometrial cancer remains pure speculation, but it could provide an explanation for a reduced cancer risk linked to the APOBEC3A/B deletion." (PMID 36394079, 2023). "We genotyped the APOBEC3A/B deletion in a sample of 1,470 Norwegian endometrial cancer cases and compared to 1,918 healthy controls." (PMID 36394079, 2023). "We performed stratified analyses to assess the potential differential impact of the APOBEC3A/B deletion on different histological subtypes of endometrial cancer." (PMID 36394079, 2023). "So far, the potential association between the APOBEC3A/B deletion variant and the risk of endometrial cancer has not been formally assessed." (PMID 36394079, 2023).
glioma (1 paper, 2021). A benign or malignant brain and spinal cord tumor that arises from glial cells (astrocytes, oligodendrocytes, ependymal cells). "On the one hand, we found that these genes can be clustered into eight clusters, among which APOBEC3A and APOBEC3B were isolated separately, demonstrating that different members may have different biological functions in low-grade gliomas." (PMID 34638749, 2021).
influenza (1 paper, 2021). An acute viral infection of the respiratory tract, occurring in isolated cases, in epidemics, or in pandemics; it is caused by serologically different strains of viruses (influenzaviruses) designated A, B, and C, has a 3-day incubation period, and usually lasts for 3 to 10 days. "Here we find that APOBEC3A-mediated cellular RNA editing can also be induced by influenza or Maraba virus infections in normal human macrophages, and by interferons in tumor-associated macrophages." (PMID 33483601, 2021).
kidney cancer (1 paper, 2019). Primary or metastatic malignant neoplasm involving the kidney. "In contrast, our results showed that germline APOBEC3A/B deletion was significantly associated with an increased expression level of uc011aoc (APOBEC3A/B) across all cancer types, except for stomach, pancreas and kidney cancers." (PMID 31533728, 2019). "In comparison with the associations from APOBEC3A, APOBEC3B was specifically associated with APOBEC-mutational signature in stomach, pancreas and kidney cancers, with a P = 5.2 × 10− 11, P = 2.0 × 10− 3, and P = 1.1 × 10− 4, respectively." (PMID 31533728, 2019). "Likewise, an additional association for uc011awn (APOBEC3A) was observed in thyroid, while associations for uc003awo (APOBEC3B) were observed in stomach, pancreas and kidney cancers." (PMID 31533728, 2019).
melanoma (1 paper, 2018). A malignant, usually aggressive tumor composed of atypical, neoplastic melanocytes. "However, the role for APOBEC3 in melanoma mutagenesis has also been established in a subset of melanomas, and experimental evidence has suggested an important role of APOBEC3A generating mutations specific to skin lesions." (PMID 29642934, 2018).
metastatic tumors (1 paper, 2020). "Given that decreased APOBEC3A levels were observed as CES‐R/M group‐specific features and as unfavorable clinical outcome‐predicting features, it is assumed the APOBEC activity is repressed in metastatic tumors and may predict the disease progression and metastasis in CES with HPV infection." (PMID 33017516, 2020).
myeloid leukemia (1 paper, 2024). A clonal proliferation of myeloid cells and their precursors in the bone marrow, peripheral blood, and spleen. "THP1 (myeloid leukemia) cells with integrated doxycycline (dox)-inducible APOBEC3A transgene (THP1-A3A) and constitutive Cas9 transgene were transduced with the Brunello guide RNA (sgRNA) lentiviral library which includes multiple sgRNAs for each human gene as well as non-targeting control sgRNAs." (PMID 38886582, 2024).
non-small cell lung carcinoma (1 paper, 2024). A group of at least three distinct histological types of lung cancer, including non-small cell squamous cell carcinoma, adenocarcinoma, and large cell carcinoma. "In the NCI-H2347 non-small cell lung cancer cell line, we found that type I interferon (IFN) treatment upregulated endogenous APOBEC3A expression which correlated with an increase in replication tract length." (PMID 38886582, 2024).
oral squamous cell carcinoma (1 paper, 2017). "We thus report a frequent APOBEC mutational profile, which relates to a APOBEC3B-deletion germline polymorphism in Taiwanese oral squamous cell carcinoma that impacts expression of APOBEC3A, and is shown to be of clinical prognostic relevance." (PMID 28878238, 2017).
preeclampsia (1 paper, 2022). Preeclampsia is a hypertensive disorder of pregnancy that is characterized by new-onset hypertension with proteinuria presenting after 20 weeks of gestation, and depending on mild or severe forms may initially present with severe headache, visual disturbances, and hyperreflexia. "The aberrant copies of APOBEC3A, APOBEC3A_B, BTNL3, and LMF1 between preeclampsia patients and controls were verified by quantitative polymerase chain reaction." (PMID 35651912, 2022).
schizophrenia (1 paper, 2024). A major psychotic disorder characterized by abnormalities in the perception or expression of reality. "TET1 expression was increased, while APOBEC3A and APOBEC3C expression was decreased in the frontal cortex of schizophrenia patients, suggesting that the disruption of the DNA methylation and demethylation pathways may contribute to elevated 5hmC levels in schizophrenia patients." (PMID 38203806, 2024).
Sepsis (1 paper, 2023). Sepsis is defined as life-threatening organ dysfunction caused by a dysregulated host response to infection. "Notably, the key genes upregulated during sepsis are responsible for regulating cell cycle progression and differentiation (i.e., S100A8 and S100A9) and immune responses (i.e., ANXA1, APOBEC3A, LILRA5, CR1, and CD55)." (PMID 37298316, 2023).
skin cutaneous melanoma (1 paper, 2019). "An overwhelming excess of somatic mutations in APOBEC1 and APOBEC3A/B/G mutable motifs is likely to be due to the known excess of mutations in dipyrimidine dinucleotides (for example, TC) in skin cutaneous melanoma caused by mutagenic UV photoproducts." (PMID 30759888, 2019).
squamous intraepithelial lesions (1 paper, 2023). "High-grade squamous intraepithelial lesions (HSILs) had higher APOBEC3A expression than low-grade squamous intraepithelial lesions (LSILs) (P < 0.01)." (PMID 38021159, 2023).
tongue SCC (1 paper, 2025). "Among those cell lines profiled by the CCLE, APOBEC3A and GRHL3 mRNA levels were highest in BICR6 and BICR22; lines derived from an SCC of the hypopharynx and from a lymph node metastasis from a tongue SCC respectively (Fig. EV3B)." (PMID 39548236, 2025).